IL6 (interleukin 6)
Diseases named in the same sentence as IL6 in open-access papers (continued):
Sharing a sentence is not in itself a finding about the gene and the disease.
head and neck squamous cell carcinoma (59 papers, 2008 to 2026). A squamous cell carcinoma that arises from any of the following anatomic sites: lip and oral cavity, nasal cavity, paranasal sinuses, pharynx, larynx, and salivary glands. "A study observed that an increase in IL-6 in head and neck squamous cell carcinoma was associated with cisplatin resistance." (PMID 31117164, 2019). "Higher concentrations of IL-6 in the serum and other biological fluids are reported in patients with head and neck squamous cell carcinoma (HNSCC)." (PMID 38396821, 2024). "Under a hypoxic microenvironment, vascular endothelial growth factor (VEGF) and IL-6, generated by head and neck squamous cell carcinoma (HNSCC) attract macrophages and polarize them to the M2 type." (PMID 36071472, 2022). "Inhibition of IL-6 or IL-8 using neutralizing antibodies significantly reduced CAF-induced autophagy in mouse xenograft models of head and neck squamous cell carcinoma, supporting a role for IL-6 and IL-8 in autophagy." (PMID 34858425, 2021). "Twist1 expression is upregulated in head and neck squamous cell carcinoma (HNSCC) cell lines treated with interleukin 6 (IL-6)." (PMID 33808323, 2021). "Similar to our results, higher production of IL-6 has been reported in CSCs of head and neck squamous cell carcinoma." (PMID 33426090, 2020). "Squamous cell carcinoma of the head and neck (SCCHN) patients with low interleukin 6 (IL-6) and high MMP9, or with high IL-6 and low MMP9, were found to have the poorest outcomes followed by patients with both high IL-6 and high MMP9." (PMID 32545247, 2020). "A recent study reported that specific EGFR tyrosine kinase inhibitor erlotinib induce IL-6 expression in head and neck squamous cell carcinoma through NOX4/p38 and JNK/ NF-κB pathway." (PMID 26513016, 2015). "The increased levels of serum IL-6 in patients with head and neck squamous cell carcinoma (HNSCC) compared to the healthy controls have been found in previous reports." (PMID 25858079, 2015). "We have recently showed that cancer stem cells reside in the perivascular niche of head and neck squamous cell carcinomas, and that endothelial cell-secreted IL-6 enhances the survival, self-renewal, and tumorigenic potential of cancer stem cells." (PMID 26287605, 2015). "We have recently demonstrated that endothelial cell-secreted IL-6 regulates tumor growth and the tumorigenic potential of cancer stem cells in head and neck squamous cell carcinomas." (PMID 26287605, 2015). "Accuracy was demonstrated by determining IL-6 and IL-8 in conditioned media from head and neck squamous cell carcinoma (HNSCC) cells and comparing results to those from standard single-protein ELISAs." (PMID 24482763, 2013). "It has reported that the addition of pembrolizumab to docetaxel and cisplatin (TP) ex vivo leads to a greater suppression of monocyte chemoattractant protein 1 (MCP-1), interferon-γ (IFN-γ), and interleukin-6 production in head and neck squamous cell carcinoma than what is observed with TP alone." (PMID 41394850, 2025). "Like in head and neck squamous cell carcinoma, Interleukin-6, a representative inflammatory cytokine, could induce ferroptosis resistance by IL-6/STAT3/xCT axis." (PMID 39483473, 2024). "Furthermore, we chose to analyze the role of IL-1α and IL-6 due to their known implication in head and neck squamous cell carcinoma development, while IL-17 was chosen due to its known role in fibrotic changes, which often characterize oral lesions from both GVHD and LPO." (PMID 39728035, 2024). "IL-6 reversed ferroptosis and growth inhibition induced by xCT knockdown or erastin in head and neck squamous cell carcinoma (HNSCC) but promoted ferroptosis in bronchial and mammary epithelial cells." (PMID 36407322, 2022). "Recent studies have shown that IL-6 signaling plays an important role in the aggressive and metastatic phenotype of head and neck squamous cell carcinoma (HNSCC)." (PMID 28978005, 2017).
head and neck squamous cell carcinoma (continued). "Both bacteria have also been shown to induce IL-6 production, which appears to play a pivotal role in the tumor microenvironment of OSCC and other head and neck squamous cell carcinomas." (PMID 40944094, 2025). "In head and neck squamous cell carcinoma, VEGF-A promotes tumour proliferation by upregulating BEST1 expression in monocytes and enhancing the secretion of cytokines such as IL-6 and IL-8." (PMID 41249152, 2025). "Conversely, blocking the IL-6/JAK2/STAT3 pathway can inhibit the progression of precancerous vocal cord (oral) leukoplakia and delay the occurrence of head and neck squamous cell carcinoma (HNSCC) tumors." (PMID 37666813, 2023). "Besides, in head and neck squamous cell carcinoma (HNSCC) cells, IL-6 has been shown to activate the Akt, Erk1/2 and STAT3 pathways, but EMP promotion was demonstrated to be mediated specifically by the JAK/STAT3 pathway." (PMID 34361105, 2021). "In squamous cell carcinomas of the head and neck (HNSCC), triggering the TLR3 signaling pathway along with cisplatin induces production of the proinflammatory cytokines IFN-β, IL-6, and CCL5 to promote cellular survival." (PMID 33072559, 2020). "Another interesting study involved Temoporfin-PDT in head and neck squamous cell carcinoma (HNSCC), where increased serum levels of IL-6 were detected with a peak at 24 h, and HMGB1 with a peak at one week after treatment, further supporting PDT as a potent inducer of acute inflammation." (PMID 31991650, 2020). "Yadav et al46 found that myoferlin is bound to EHD2 protein and modulates the IL‐6/STAT3 signalling pathway, which regulates the expression of IL‐6/STAT3 downstream genes, including snail and nanog, in head and neck squamous cell carcinoma (HNSCC) cell lines." (PMID 31475450, 2019). "In a recent study by Lambert and colleagues, low pre-treatment serum IL-6 associated with prolonged PFS (p = 0.011) in a univariate analysis of the anti-PD-1 inhibitor budigalimab in patients with advanced NSCLC (n = 40) or head and neck squamous cell carcinoma (HNSCC; n = 41)." (PMID 38493133, 2024). "Moreover, in head and neck squamous cell carcinoma (HNSCC), TTP down-regulation enhances the stability of mRNAs, promotes IL-6 and VEGF secretion and significantly increases cellular invasion in cancers by increased secretion of IL-6 and MMP-2/9." (PMID 30850014, 2019). "On an equal footing, stromal interleukin IL-6 defines the tumorigenic capacity of cancer stem cells (CSC) sorted from primary human head and neck squamous cell carcinoma (HNSCC) and transplanted into mice." (PMID 25590298, 2015).
hyperuricemia (59 papers, 2013 to 2026). An abnormally high level of uric acid. "Sedentary behavior increases hyperuricemia risk by elevating proinflammatory cytokines (IL-6, CRP, TNF-α) and reducing anti-inflammatory markers (IL-RA)." (PMID 41404102, 2025). "Hyperuricemia has been associated with increased levels of pro-inflammatory cytokines, such as interleukin-6 (IL-6) and tumor necrosis factor-alpha (TNF-α)." (PMID 39070258, 2024). "Therefore, we introduced sIL-6R to demonstrate that hyperuricemia-induced STAT3 activation is associated with IL-6." (PMID 40361044, 2025). "Data in the literature suggest that even asymptomatic hyperuricemia is associated with a proinflammatory status and increased levels of CRP, IL-6, and neutrophils." (PMID 40428204, 2025). "In our study, hyperuricemia significantly induced IL-6 mRNA expression in AC16 cardiomyocytes, and immunohistochemical analysis of myocardial tissue from hyperuricemic mice also revealed increased IL-6 levels." (PMID 40361044, 2025). "Clinical studies have shown that patients with hyperuricemia have significantly higher levels of inflammatory factors such as interleukin (IL-6) than do those with normal uric acid levels." (PMID 40361044, 2025). "Patients receiving CAR T-cell therapy can develop fulminant HLH and present with increased lactate dehydrogenase, hyperuricemia, IL-10, IL-6, and IFN-γ." (PMID 37010812, 2023). "Despite some limitations, this study revealed significant correlations between ghrelin and leptin, between these hormones and IL-6, and between leptin and UA in patients with hyperuricemia, urolithiasis and MetS." (PMID 36830821, 2023). "Ruminococcus positively correlated with TJ proteins (ZO-1), in contrast, negatively correlated with inflammatory cytokines (IL-1β and IL-6), LPS, and UA, indicating Ruminococcus had a positively effect on hyperuricemia." (PMID 33104864, 2021). "Clinical trials have shown that serum levels of IL-6 and TNF-α are significantly higher in hyperuricemia patients than in healthy people, and that of IL-6 and TNF-α are significantly increased as sUA levels increase." (PMID 33568990, 2020). "Experimental studies have shown that hyperuricemia leads to elevated levels of agents of systemic inflammation such as interleukin 6 (IL-6), tumor necrosis factor a (TNF-a) and C-reactive protein (CRP)." (PMID 31815071, 2019). "Asymptomatic hyperuricemia is a pro-inflammatory condition affiliated with elevated levels of serum markers of inflammation, such as C-reactive protein, interleukin-6 and neutrophil count." (PMID 28523032, 2017). "Consequently, hyperuricemia increased IL‐6 pathway activity in ITM2B‐expressing allografts, whereas this effect was diminished in ITM2BI115A‐expressing allografts." (PMID 41319268, 2026). "As expected, the concentrations of multiple inflammatory cytokines including tumor necrosis factor-alpha (TNF-α), interleukin-1 beta (IL-1β) and interleukin-6 (IL-6) were higher in the kidney of the hyperuricemia group than those in the CON group, indicating the presence of inflammation." (PMID 41009565, 2025). "Additionally, serum levels of inflammatory cytokines (IL-1β, IL-6) were notably elevated, indicating severe kidney tissue reactions and confirming the presence of uric acid nephropathy in hyperuricemia mice." (PMID 38257077, 2024). "Moreover, it lessens renal concentrations of TNF-α, IL-1β, and IL-6 in mouse models of hyperuricemia, thereby mitigating renal impairment." (PMID 38094893, 2023). "Besides, the urate‐associated inflammation reflected by IL‐6, TNF‐α and diamine oxidase (DAO) levels in serum of hyperuricemia rats were also alleviated." (PMID 36925686, 2023). "Hyperuricemia is accompanied by inflammatory markers, including IL-6, IL-18, hs-CRP, and TNF-α." (PMID 35453642, 2022).
hyperuricemia (continued). "In comparison to the CON group, the mRNA levels of inflammatory and stress markers, including IL-1β, TNF-α, and IL-6, were approximately twofold higher (p < 0.001) in the hyperuricemia group, indicating a significant upregulation of these genes in response to hyperuricemia (HUA)." (PMID 41009565, 2025). "Furthermore, past research showed that PO-induced hyperuricemia rats (250 mg/kg, rats) could display increases in IL-6 and other inflammation indicators." (PMID 36432519, 2022). "In addition, many studies reported that hyperuricemia was associated positively with TNF-α, IL-6 and CRP, which suggested that uric acid may have a role in inflammation and subsequent inflammatory related diseases." (PMID 29498657, 2018). "Clinical data indicate that patients with hyperuricemia or uric acid nephropathy exhibit significantly higher levels of low-grade inflammatory markers, such as hs-CRP, TNF-α, and IL-6, in their serum compared to healthy individuals." (PMID 40771212, 2025). "Hyperuricemia triggers systemic inflammation through ROS-mediated NF-κB activation and peroxidase inhibition, elevating TNF-α, IL-6, and IL-1β." (PMID 40870677, 2025). "The polyphenols extracted from purple potato leaves inhibited the levels of IL-1β, IL-6, and TNF-α, as well as serum creatinine, and also decreased the levels of expression of XOD in the liver of hyperuricemia mice, thus protecting the kidney." (PMID 38674582, 2024). "The geniposide-phospholipid complex reduces levels of inflammatory cytokines (TNF-α, IL-6, and IL-1β) in hyperuricemic mice and regulates the PI3K/AKT/NF-κB signaling cascade to improve post-hyperuricemia chronic kidney disease." (PMID 38094893, 2023). "Berberrubine has been shown to significantly reduce serum urate levels and the levels of inflammatory mediators (IL-1β, IL-6, and TNF-α) in mice with PO- and hypoxanthine-induced hyperuricemia." (PMID 36483739, 2022). "NAY significantly reduced the level of UA in hyperuricemia mice and cells by inhibiting xanthine oxidase activity and reduced the levels of TNF-α, IL-6, and other inflammatory factors in serum and kidney of mice." (PMID 36120294, 2022). "In some patients with asymptomatic hyperuricemia, steady hyperuricemia is suggested to be sufficient to trigger MSU crystal deposition and MSU crystals can trigger inflammatory pathways (IL-6 and IL-8)." (PMID 33854690, 2021). "The production of IL-1β, IL-6 and ICAM-1 was also decreased in the WPP-treated group and CPP-treated group to inhibit the inflammatory process in hyperuricaemia." (PMID 35087407, 2021). "The ICAM-1, IL-1β and IL-6 levels were measured to evaluate the anti-inflammatory effects of WPP and CPP on the treatment of hyperuricaemia." (PMID 35087407, 2021). "Remarkably, the expression and synthesis of IL-6 and IL-8 induced by PRP are decreased significantly in the presence of hyperuricemia." (PMID 25276832, 2014). "The synthesis of IL6 and IL8 proteins induced by PRP is decreased significantly in the presence of hyperuricemia (P = 0.017 and P = 0.012, resp)." (PMID 25276832, 2014). "There have studies indicated that the levels of inflammatory markers, including interleukin-6 (IL-6), tumour necrosis factor-α (TNF-α) and transforming growth factor-β1 (TGF-β1), are markedly elevated in individuals with hyperuricaemia in comparison to those in a healthy state." (PMID 39258191, 2024). "In this study, we evaluated the therapeutic potential of WPP and CPP in the treatment of hyperuricaemia by measuring XO activity inhibition, the levels of UA, Cr and UN in serum and urine and the expression of ICAM-1, IL-1β and IL-6, and by observing kidney histological damage." (PMID 35087407, 2021). "Hyperuricemia can promote the expression of inflammatory cytokines, such as IL-1β, TNF-α, and IL-6." (PMID 34444825, 2021).
hyperuricemia (continued). "Furthermore, bergenin decreased the serum levels of IL-6, IL-1β, and TNF-α in hyperuricemia mice, and promoted a polarization shift from the M1 to M2 phenotype in RAW264.7 cells." (PMID 32850823, 2020). "Interleukin-6 (IL-6), tumor necrosis factor-alpha (TNF-α), and high sensitive C-reactive protein (hs-CRP) were also measured in order to determine the relationship of indices of inflammation with VAI and hyperuricemia." (PMID 29734946, 2018). "It is noteworthy that hyperuricemia may stimulate inflammatory leukocytes through epigenetic modification such as histone methylation, even without MSU crystals, thereby increasing production of IL-1β, IL-6, and TNF-α." (PMID 33568990, 2020). "In controls, associations with hypoalphalipoproteinemia, non-HDL-C, apolipoprotein B, hyperuricemia, TNF-α, IL-6, IL-15, valvular calcification, and subclinical hypothyroidism were observed." (PMID 33802675, 2021). "On the other hand, in controls, the polymorphisms were associated with hypoalphalipoproteinemia, non-HDL cholesterol, apolipoprotein B, hyperuricemia, TNF-α, IL-6, IL-15, valvular calcification, and subclinical hypothyroidism." (PMID 33802675, 2021). "In addition, there were higher values of SBP, DBP, WC, BMI, TG, LDL, FBG, insulin, HOMA-IR, SCr, cystatin C, NAG, hs-CRP, IL-6, and RBP4 in the hyperuricemia group compared to the non-hyperuricemia group (P<0.05), but lower values of HDL, eGFR, and serum uric acid (P<0.001)." (PMID 35846279, 2022). "Finally, considering the economic feasibility of epidemiological study, traditional inflammation markers such as CRP, ferritin and interleukin 6, which could be used to compare the predictive power with MHR for hyperuricemia, were not collected in present study." (PMID 32178680, 2020).
lymph node metastasis (59 papers, 2004 to 2026). "Although not presented in the results section, additional analysis specifically examining postoperative CIP revealed that impaired pulmonary function, lymph node metastasis, and elevated preoperative IL-6 levels remained significantly associated." (PMID 41100188, 2025). "We also demonstrated that serum IL-6 levels were associated with histological grade and lymph node metastases." (PMID 36693957, 2023). "On multivariable logistic regression modeling, elevated preoperative plasma levels of both IL6 and IL6sR were significantly associated with an increased risk of ≥ pT3 disease, lymph node metastasis and any NOCD (p-values < 0.03)." (PMID 34023914, 2022). "Of note, patients with high intratumoral CD45+Rab37+IL-6+ expression were significantly associated with advanced tumor stage (P < 0.001), lymph node metastasis (P = 0.025) and distal metastasis (P = 0.003)." (PMID 34093869, 2021). "Plasma concentrations of IL-6 and Ca199 are associated with lymph node metastasis and CRP with stage, size, lymph node, and distant metastases." (PMID 33144870, 2020). "In turn, in these conditions, coexpression of IL-6 would increase the risk of lymph node metastases by eliciting MDSCs activity and suppressing cytotoxic T-cell function." (PMID 31885577, 2019). "A recent study reported that IL‐6 expression was associated with cell invasion, death, and lymph node metastasis in CRC." (PMID 31246342, 2019). "Previous studies showed similar results where the IL-6 and IL-8 cytokines were associated with increased lymph node metastases and reduced survival." (PMID 31007849, 2019). "The associations of the serum levels of IL-6, P. gingivalis IgG, and F. nucleatum IgG with clinical stage and pathological features, including lymph node metastasis, were also assessed by testing the mean differences, and this analysis also showed negative results." (PMID 31167516, 2019). "Additionally, IL-6 activates the RhoA and phosphorylated-Src protein, which is associated with aggressive lymph node metastasis and poor survival in malignancy." (PMID 23117246, 2013). "Moreover, IL-6 may be considered as a predictive risk biomarker of CRC recurrence due to its relationship with lymph node metastasis, which is still recognized as the most gainful prognostic factor." (PMID 34441316, 2021). "Certainly, in their multivariate analyses, both IL-6 and IL-6sR emerged as independent predictors of lymph vascular invasion, lymph node metastasis, disease recurrence, and disease-specific survival." (PMID 41590518, 2026). "A significant correlation was observed between the serum concentration of IL-6 and the tumour stage, depth of tumour invasion, lymphatic invasion, and venous invasion, as well as lymph node metastasis." (PMID 38398148, 2024). "Serum levels of TNF-α and IL-6 were significantly increased when tumor length was > 5 cm, depth of invasion into the serosal layer, and lymph node metastasis occurred, consistent with previous findings." (PMID 37430251, 2023). "They found that serum IL-6 significantly correlated with the lymph node metastasis and liver metastasis; the serum IL-8 levels also tended to associate with the lymph node recurrence." (PMID 37345096, 2023). "Regarding lymph node metastasis, IL-1β and IL-6 demonstrated increasing levels with an advancement in the N stage, IL-6 demonstrating the most important differences between N stages." (PMID 38137862, 2023). "We found that lymph node metastases, pathological stage, molecular classification, VEGFR2 expression by IHC, MVD by IHC, and circulating sTIE2, IL-6, and IL-8 were significantly associated with prognosis." (PMID 37577519, 2023). "In the case of lymph node metastasis and distant metastasis, our study confirmed that BC patients with N0 and M0 status showed higher IL-6 expression than BC patients with ≥N1 and M1 status (p < 0.01)." (PMID 37047238, 2023).